CXCL10 (C-X-C motif chemokine ligand 10)
Diseases named in the same sentence as CXCL10 in open-access papers (continued):
Sharing a sentence is not in itself a finding about the gene and the disease.
tumor (continued). "Based on our initial hypothesis, CXCL10-mucin-GPI should be able to recruit leukocytes in the absence of an inflammatory reaction, thereby overcoming endothelial cell anergy within tumor tissues." (PMID 24023642, 2013). "According to our hypothesis, recombinant fusion proteins such as CXCL10-mucin-GPI when injected into a solid tumor, incorporate into the cell membranes of tumor, stromal and endothelial cells." (PMID 24023642, 2013). "The tumor evasion from CXCR3+ cells is probably not dependent on chemokine production by the tumor since CXCR3 ligands CXCL10 and CXCL11 both are present in higher concentrations in the tumor." (PMID 22319577, 2012). "CXCL10, at the same time, attracts CXCR3-expressing Th1 cells to the tumor site." (PMID 22408433, 2012). "The increased expression of IFNγ in the bladder at day 7 is probably due to CXCL10 being secreted by the tumor cells, but MB49 itself does not express IFNγ." (PMID 22013484, 2011). "EpCAM, IL8, CXCL10/IP10, CCL3/MIP-1α, CCL4/MIP-1β, CCL15/MIP-1δ, PDGFR-B protein were found to be expressed predominantly in tumours only, suggesting that they could be involved in the later stages of gastric tumorigenesis." (PMID 21092330, 2010). "The expression of CXCR3 receptors by CRC human tissues and by the human HT29 cells and the murine C26 tumour cells has led us to determine the ability of the corresponding ligands, CXCL9, CXCL10 and CXCL11 to affect the growth and chemotactic responses of HT29 and C26 cells in vitro." (PMID 19436305, 2009). "Given that IP-10/CXCL10 and MIG/CXCL9 are important for CCL21-DC mediated tumor regression in murine studies, we examined whether AdCCL21 transduction increased the expression of these chemoattractants in human DC." (PMID 18644162, 2008). "Likewise, interferon response genes (including TLR3, MX1, RSAD2, IFI44, IFI27, IFIT1, and IFIT3), and chemokine genes (including CCL7, CXCL10, CXCR1, and CCL25) were significantly increased in PM-treated MM tumor tissues, whereas panobinostat showed minimal effects at equivalent doses." (PMID 40562746, 2025). "Second, tumor subsets enriched for microenvironment features, including hypoxia markers (e.g., Slc2a1, Pdk1, Car9), extracellular matrix (ECM) genes (e.g., Matn2, Fn1, Dcn, Col6a1), vasculature (e.g., Cdh5, Pecam1, Vwf), and interferon response genes (e.g., Rsad2, Ifit3, Gbp3, Cxcl10, Cd274)." (PMID 40171265, 2025). "Given CXCL10’s canonical role as a chemoattractant, local elevation of CXCL10 within OS lesions may also facilitate recruitment of CXCR3+ circulating monocytes and macrophages, amplifying the immunosuppressive and tumor-promoting microenvironment." (PMID 41516196, 2025). "Consistently, lacidipine treatment or co‐administration with DOX/cisplatin significantly increased the mRNA expression of CCL5, CD274, CXCL10, and CXCL11 and decreased CCL2 mRNA levels in tumor tissues, thereby promoting immune cell infiltration and converting the “cold” into a “hot” tumor." (PMID 39585774, 2025). "To investigate whether tumours themselves might drive changes in the microenvironment, we treated WT B16-OVA with IFNγ for the indicated period and assessed the expression of a panel of cytokines, for which only CXCL10 was found to be induced by IFNγ." (PMID 39746898, 2025). "However, CXCL10 and CXCL11 can also increase tumor proliferation and metastasis." (PMID 40129606, 2025). "Cisplatin-triggered ferroptotic tumor cells reprogram TANs toward an N1-like phenotype, characterized by the upregulation of cytotoxic effectors such as TNF-α, granzyme B, and NE, as well as chemokines and cytokines including CCL2, CCL3, CXCL9, CXCL10, CXCL11, IL-12A, and IL-12B." (PMID 40805288, 2025). "Notably, CXCL9, CXCL10, and CXCL11 utilize the shared receptor CXCR3 and engage in similar mechanisms that facilitate the recruitment of T cells and other immune cells to the tumor microenvironment, contributing to antitumor responsiveness." (PMID 40909948, 2025).
tumor (continued). "Current therapeutic strategies aim to exploit the immunostimulatory properties of CXCL10 through gene therapy, nanoparticle-based delivery or cytokine-induced upregulation to enhance immune cell infiltration, increase IFN-γ production and promote vascular normalization in the tumor microenvironment." (PMID 40760734, 2025). "Based on these transcriptomic results, suppression of CCN2, FGFR2, and SELE may inhibit tumor proliferation, metastasis, or angiogenesis, while upregulation of CDH1 and CXCL10 could enhance cellular adhesion and antitumor immune responses, offering promising avenues for therapeutic intervention." (PMID 40724877, 2025). "Irradiated tumor cell–derived exosomes display strong immunogenic activity, inducing IFN-related genes (IFN-β, Mx1, IFNAR1) in DCs and stimulating the release of IFN-β, IL-6, and CXCL10, which together promote an inflammatory niche that supports T cell priming." (PMID 41204180, 2025). "CRISPR-mediated CXCL10 knock-in enhances CAR T cell infiltration and antitumour efficacy in vitro and in vivo, including humanized CD34+ HuNOG mice, where CXCL10-expressing tumours show stronger immune infiltration and prolonged tumour control within a reconstituted human immune microenvironment." (PMID 41366257, 2025). "We also observed that tumor cells that engaged senescence-related transcriptional programs, or “Sen-High” cells, upregulated IFN-γ signaling machinery, including Ifngr1, Ifngr2, Jak1, Jak2, Irf1, and Stat1, as well as IFN-γ target genes Cxcl9, Cxcl10, and Tap1." (PMID 40299790, 2025). "Building upon prior research suggesting that chemokines like C-X-C motif chemokine ligand 9 (CXCL9) and C-X-C motif chemokine ligand 10 (CXCL10) recruit CAR-NK cells, we hypothesized that tumor cell m6A methylation, regulated by Methyltransferase-like 3 (METTL3), influences chemokine secretion." (PMID 39497707, 2025). "Interestingly, ORMDL3 expression showed a negative correlation with CD8+ T cell activation markers such as PRF1, GZMA, and GZMB, as well as with ISGs such as CCL5 and CXCL10, validating our finding that ORMDL3 serves as a negative regulator of the IFN signaling pathway and anti-tumor immunity." (PMID 40126553, 2025). "Simultaneously, IFN-γ induces the expression of chemokine ligands such as CXCL9 and CXCL10, which bind to the CXCR3 receptor on effector T cells and NK cells, promoting their robust infiltration into the tumor microenvironment and effectively suppressing tumor growth." (PMID 41359111, 2025). "Furthermore, we dissected the contribution of PBRM1 deletion in CRC by regulating inflammatory factors, such as CCL5 and CXCL10 chemotaxis, and activating cytotoxic T cells and killer NK cells, which express NKG2D in the tumor microenvironment through activation of the NF-κB signaling pathway." (PMID 40093909, 2025). "Finally, the correlation between CXCL10 and CXCL11 and tumor immune invasion was analyzed." (PMID 40129606, 2025). "TNFɑ was also positively correlated with tumor burden (r = 0.6094, p = 0.0465), though not as strongly as CXCL10 or CCL2, indicating that higher serum levels of these cytokines may be associated with higher severity of disease." (PMID 39623404, 2024). "Using isolated tumor tissue, we analyzed gene expression related to cytotoxicity (Perforin, Granzyme B, Granulysin, and FasL), inflammatory or chemotactic cytokines (IFN-γ, CXCL9, CXCL10, and CXCL11), and CD8+ T cell activation and proliferation (CD69, Tbx21, IL-2, and IL-12b)." (PMID 39066478, 2024). "CXCL9 and CXCL10 are well known IFN-γ-inducible chemokines produced by endothelial cells, monocytes/macrophages and fibroblasts in the tumor microenvironment and prevent tumor angiogenesis by blocking endothelial cell proliferation, inducing tumor necrosis 32-35." (PMID 39629126, 2024).
tumor (continued). "Radiotherapy also induces the expression and release of chemokines such as CXCL9, CXCL10, and CXCL16 in tumor cells, promoting the migration of effector T lymphocytes to tumor sites, modulating the immune status of the TME, and activating the body’s anti-tumor immune response." (PMID 38809459, 2024). "Even in the presence of high concentrations of C-X-C motif chemokine ligand 10 (CXCL10) or C-X-C motif chemokine ligand 4 (CXCL4), a T-cell chemoattractant, the infiltration of T cells in the TME is blocked due to the hypercrosslinked collagens and dense glycoproteins surrounding the tumor cells." (PMID 38946426, 2024). "Through intratumoral injection, the functional chemokine CXCL10 is continuously expressed in the TME, attracting more CXCR3 + T cells there to kill tumor cells, and the recombinant adenovirus exhibits excellent ability to 'fire up' the TME and improve the anti-tumor efficiency of PD-1 antibodies." (PMID 38243252, 2024). "With these cells, we set up a transwell migration assay whereby activated CD8+ T cells were seeded in the top chamber, on top of a monolayer of either glyCAF or non-glyCAF and allowed to migrate towards a gradient of CXCL10 and Ccne1+ tumor cells in the bottom chamber." (PMID 38509063, 2024). "Furthermore, IFN-γ produced by tumor-infiltrating CAR-T-cells led to the recruitment and activation of iNOS+ tumor macrophages, further upregulating the expression of the CXCR3 ligands CXCL9 and CXCL10." (PMID 38397092, 2024). "Serum IFNy in Arm C also positively correlated with CXCL10 and IL-17, further underscoring that a lack of T cell infiltration into the tumor was not limiting for outcomes in the group of patients with high baseline serum IFNy treated with the sandwich approach." (PMID 38167503, 2024). "In this regard, the in vitro data suggest that the free bacteria or the infected tumor cells present into the TME are capable to stimulate the activation of macrophages and the release of cytokines and chemokines (TNF-α, IL-6, IL-12, and CXCL10) in a MyD88-dependent manner." (PMID 38835781, 2024). "GBE1 knockdown can promote the secretion of CCL5 and CXCL10, and the recruitment of CD8+ T lymphocytes into the tumor microenvironment, suggesting that GBE1 may be an important target to inhibit the progression of LUAD tumor through immunotherapy." (PMID 37187527, 2023). "The 4-culture tumor spheroids were characterized by spatial proximity of PSC and monocytes to the endothelial cells and a cytokine signature with increased concentrations of CXCL10, CCL2, and IL-6, which have been observed in PDAC patients and associated with poor survival." (PMID 37519820, 2023). "This was preceded by acute decreases in proliferating tumor-infiltrating and peripheral T cells and a rapid proliferative rebound after ATRi cessation, increased inflammatory signaling (IFN-β, chemokines, particularly CXCL10) in tumors, and an accumulation of inflammatory cells in the DLN." (PMID 36810257, 2023). "Exogenously administered IL-33 increased the expression of alarmins, Th2 chemokines (CCL17 and CCL22), CD8 + T cell chemokines (CXCL10, CX3CL1), eosinophil chemokines (CCL11, CCL13, CCL24), as well as Th2-related cytokines (IL-4, IL-13) and Th1 effector molecules (granzyme B) in the primary tumor." (PMID 37587450, 2023). "Moreover, CXCL10 and matrix metalloproteinases, activated in response to IRI, enhance regulatory T cells migration and consequent immune response suppression, which ultimately supports tumor growth." (PMID 37240873, 2023). "Tumours from patients with durable responses are enriched for PDL1+ CXCL10+ macrophages and, based on cell–cell interaction analysis, express high levels of CXCL9/10/11 and are predicted to attract peripheral CXCR3+ CD8+ effector-memory T cells (CD8 TEM) into the tumour." (PMID 38030622, 2023). "Furthermore, CXCL10 induces chemotaxis of CXCR3+ NK cells, resulting in tumor regression." (PMID 38035101, 2023).
tumor (continued). "The expression of four TME-related genes (CXCL10, LZTS2, IDO1, and MAB21L2) that predict the TME signature of CRC was validated in four GEO datasets: GSE20916 (145 samples), GSE21815 (141 samples), GSE3629 (121 samples), and GSE89287 (71 samples), which contained normal control and tumor samples." (PMID 37596528, 2023). "Moreover, RNA-seq results showed that NAT10 promoted the transcription of multiple critical cytokines such as CXCL3 and CXCL8 and suppressed CXCL10, CXCL11 and so on, which are important for the recruitment of immune cells, angiogenesis, tumor microenvironment remodeling, and cancer progression." (PMID 37914704, 2023). "Furthermore, FLOT1 depletion-boosted DNA damage activated STING signaling pathway and promoted the production of CCL5 and CXCL10 that can drive CD8+ T lymphocytes chemotaxis, thereby reprogramming tumor immune microenvironment and triggering the antitumor immune response." (PMID 37131290, 2023). "Therefore, cancer cells overexpressing A3A augment anti-tumor immune response might by secreting CCL5 and CXCL10 to recruit and activate CD8+ T cells in ESCC, which warrants further functional investigations." (PMID 37215984, 2023). "Therefore, we proposed a scientific hypothesis that thermal ablation treatment could induce TAM1 to express CXCL10, leading to the recruitment of CXCR3+CD8+T cells into the tumor site and enhancement of anti-tumor immunity." (PMID 36900218, 2023). "We found a negative correlation between tumour necrosis percentage and CXCL10 concentrations in mesenteric venous serum (beta = −0.460, P = 0.022), and a trend towards a negative correlation between tumour necrosis percentage and IFNG (beta = −0.363, P = 0.076)." (PMID 37031328, 2023). "The anti-PD-1 treatment could significantly inhibit MC38 tumor growth in wild-type mice, while tumor growth inhibition after anti-PD-1 treatment in Cxcl10−/− mice was not as good as in the wild-type mice." (PMID 36900218, 2023). "By contrast, expression of EZH2 in cancer cells may dampen anti-tumor immunity and hinder the infiltration of the tumor by effector T cells through EZH2- and DNMT1-mediated epigenetic silencing of TH1-type chemokines (i.e., CXCL9 and CXCL10)." (PMID 36627707, 2023). "Moreover, inhibition of COX2 by aspirin could also recruit natural killer cells and cytotoxic T lymphocytes into tumor microenvironment via increasing the secretion of CXCL9 and CXCL10." (PMID 37973900, 2023). "PGE2 can also act on human type 1 conventional dendritic cells (DCs) leading to anti-tumor dysfunction by downregulating their expression of T cell recruiting chemokine ligands such as CXCL9 and CXCL10 and production of IL-12 which could also impair NK cell function." (PMID 38022679, 2023). "In a prior study, Cxcl9 but not Cxcl10 expression by cDC1s was critical for αPD-L1 efficacy which was attributed to intratumoral T cell trafficking toward cDC1s in the tumor bed in s.c. implantable tumor models." (PMID 36472588, 2023). "In addition, higher expression of LCK has been confirmed in this work that it also upregulated the expression levels of CXCL9, CXCL10, and CXCL 11, which were reported to initiate a chemokine network to contribute to the generation of a “hot” (or T-cell–inflamed) tumor microenvironment." (PMID 36561315, 2022). "These include plasmid-borne CXCL9, intra-tumor injection of CXCL9, recombinant CXCL10 protein with adoptive cell therapy (ACT), intra-tumor injection of CXCL10, retroviral transduction tumor cells with CXCL10, and intraperitoneal injection of oncolytic vaccinia virus expressing CXCL11." (PMID 33603130, 2022). "Furthermore, inhibition of LINC00152 may increase the number of tumor-infiltrating CD8+ T cells and promote the expression of CXCL9, CXCL10, and C-X-C Motif chemokine receptor 3 (CXCR3) in xenograft tumors, thereby achieving the goal of tumor suppression." (PMID 35402261, 2022).
tumor (continued). "CCR5-CCL4/CCL5 and CXCR3-CXCL9/CXCL10/CXCL11/CXCL13 axis were significantly correlated with CD 4 T and CD 8 T cells, indicating that these chemokine–receptor pairs may recruit the T lymphocytes into tumor." (PMID 35530341, 2022). "Moreover, tumor tissues with a high T cell ratio within and close to the tumor nests in relation to the total stroma produced higher levels of CXCL9, CXCL10 and CXCL11, signifying the importance of the CXCR3-axis in T cell localization within the tumor microenvironment." (PMID 35954489, 2022). "Indeed, CXCL10 expression is enhanced by the combination therapy, thus promoting CXCR3-mediated cytotoxic T-lymphocyte infiltration and leading to a delay in hepatocarcinoma tumor growth." (PMID 36429101, 2022). "However, because CXCL10 is secreted from monocytes/macrophages and CXCR3 is expressed in lymphocytes, the selective inhibition of a signal pathway of tumor cells in immunocompetent transgenic mice is difficult, especially when immune cells and tumor cells share a common signal pathway." (PMID 36612121, 2022). "Overall, our results suggest that the establishment of an effective tumor-killing environment composed of favorable cell types, such as DCs, CD8+ memory T-cells, and NK cells, as well as important chemokines, including CCL19, CXCL10, and XCL1 relies on all aspects of the combination therapy." (PMID 36741387, 2022). "Therefore, whether LCK may promote the formation of TLSs and increase the anti-tumour function of TLSs through N1-TAN induction of CCL3, CXCL9 and CXCL10 aggregation remains to be further investigated." (PMID 36291944, 2022). "Immune cells can also directly influence the phenotype and function of tumor vessels through various cytokines, such as cytokines that inhibit tumor angiogenesis (interferon-α, interleukin-12, interleukin-18 or tumor necrosis factor) and chemokines (CXCL9, CXCL10 or CCL21)." (PMID 36569915, 2022). "Our results demonstrated that the mRNA expressions of IL-5, IL-1A, CXCL10, TNFSF4 and INHBE were significantly altered when regulating C1QTNF6, which suggested the essential implications of the cytokine-cytokine receptor interaction pathway in the process of C1QTNF6 regulating tumor progression." (PMID 35879698, 2022). "Moreover, the previous report showed that the EGFR/AKT signal could promote tumor cell proliferation through regulating immune cells, such as CD8+ T cells recruited by CXC-chemokine ligand 10 (CXCL10)." (PMID 35237300, 2022). "Our study demonstrates that CXCL10, a representative inflamed immune-response cytokine, activates CXCR3 in tumor cells to induce the phosphorylation of Src and the NF-κB subunit, p65, and the expression of HIF1-α in persistent EGFR-mutant tumor cells during EGFR-TKI treatment." (PMID 36612121, 2022). "However, Karin suggested that CXCL10 and CXCL9 may differ from other chemokines in their ability to inhibit tumor growth and enhance anti-tumor immunity." (PMID 36479091, 2022). "Cxcl9 was about threefold higher expressed in ascites in Cxcl9+ tumour-bearing mice than in the control group (median 4.58 vs. 1.45 pg/mg total protein; P = 0.003), whereas there was no significant change in Cxcl10 (median 6.62 vs. 6.07 pg/mg total protein; P = 0.90)." (PMID 35314795, 2022). "Nevertheless, taken together, this slight overall impact on tumor cell proliferation might not fully explain the significant reduction of tumor burden in Cxcl10−/− mice." (PMID 35897689, 2022). "In this eosinophil-mediated anti-tumor response, CCL11, an eosinophil-selective chemokine in the ‘eotaxin subfamily,’ was demonstrated to be cleaved by DPP4 into a truncated form (CCL113–74) with diminished chemoattractant properties, as found for CXCL10 cleavage by DPP4." (PMID 35053615, 2022).